IL25 (interleukin 25)
Diseases named in the same sentence as IL25 in open-access papers (continued):
Sharing a sentence is not in itself a finding about the gene and the disease.
tumor (continued). "Together, these results indicated that IL-25+ cells inhibited tumor progression was a predictor of favorable survival in patients with GC." (PMID 26840565, 2016). "In agreement, 4T1 cells cultured with Q2-3-treated 3T3-CM or MDA-MB-231 cells cultured with Q2-3-treated WI38-CM also showed relatively decreased cell growth activity, as compared with IL-25 protein-treated tumour cells." (PMID 27089063, 2016). "Overall, it is possible that IL-25 blockade is allowing for increased Th17 inflammation which is promoting tumor development in these mice." (PMID 27165713, 2016). "We found that acute IL-25 blockade resulted in greater tumor burdens compared to isotype control treated mice." (PMID 27165713, 2016). "In summary, we have shown that IL-25 was predominantly produced by tumor-infiltrating Mφs in the IT region of GC in situ and was regulated by TGF-β1 in vitro." (PMID 26840565, 2016). "We show herein that mice treated with an IL-25 blocking antibody developed greater tumor burdens and increased pathology than isotype treated control mice." (PMID 27165713, 2016). "The possible implications and application of our findings, in terms of the mechanistic regulation of tumour microenvironments and potential clinical inference with tumour metastasis using specific phytochemicals as IL-25 agonist, are discussed." (PMID 27089063, 2016). "To evaluate the potential role of IL-25 in tumor immunopathology, we first investigated its expression pattern in GC tissues." (PMID 26840565, 2016). "To determine the potential regulatory function of IL-25 in immune cells, we performed Spearman's rank correlation coefficient tests to assess the correlation between the density of IL-25+IT cells and tumor-infiltrating lymphocytes in GC tissues." (PMID 26840565, 2016). "Transforming growth factor-β1 (TGF-β1) has been shown to be produced by both cancer and stromal cells in tumor tissues, and to positively regulate IL-25 in the human gut." (PMID 26840565, 2016). "Altogether, we consider that the specific pharmacological activity of Q2-3 on activating IL-25 secretion in the tumour microenvironment can upregulate a strong endogenous anticancer activity." (PMID 27089063, 2016). "Investigations into the potential mechanisms showed that production of IL-25 in TSN-treated Mφs was regulated by TGF-β1 and was positively associated with effector immune cells in GC tumor tissue." (PMID 26840565, 2016). "IL-25, a proinflammatory cytokine, secreted by normal mammary epithelial cells and induces apoptosis of tumor cells via IL-25R (IL-17RB) highly expressed in tumor cells and barely expressed in normal epithelial cells." (PMID 26313265, 2015). "Injection of recombinant IL‐25 every other day produced significant anti‐tumor activity, while combining IL‐25 with chemotherapeutic or immunotherapeutic agents showed greater antitumor efficacy in human tumor xenograft models in mice compared to each agent administered alone." (PMID 38775220, 2024). "Antibodies targeting IL25 may help in neutralizing its immunosuppressive effects mediated by TCs, potentially enhancing anti-tumor immune responses." (PMID 38892399, 2024). "Overall, IL25-activated ILC2 adoptive transfer led to significant higher tumor burden." (PMID 37781372, 2023). "In the majority of cancers, IL-25 functions to support the tumor." (PMID 37005677, 2023). "IL-25 might promote tumor progression by activating multiple signaling pathways and causing downstream cell signaling cascades." (PMID 37005677, 2023). "In addition, IL-25 can interact with multiple immune cells in a complex tumor microenvironment by initiating both innate and adaptive immune responses." (PMID 37005677, 2023). "Although initially the tumor volume was similar in mice that received IL25-activated ILC2 cells and controls, it started to become significantly higher in mice that received the cells as compared to those that received vehicle after the second week of treatment." (PMID 37781372, 2023).
tumor (continued). "In this connection, it was demonstrated that IL-25, similar to IL-17A, could accelerate the proliferation and survival of tumor cells through the same oncogenic signaling pathways." (PMID 37835465, 2023). "In addition, the dysregulation of IL-25 signaling participates in cancer progression by affecting cell cycle changes, resisting apoptosis, and assisting pro-tumor cytokines." (PMID 37005677, 2023). "Thus, IL-25 is capable of promoting tumor development by activating multiple mechanistic pathways and affect different target cells in the complex tumor microenvironment." (PMID 37005677, 2023). "In conclusion, large amounts of studies indicate a role of IL-25 in tumor immunity." (PMID 37005677, 2023). "Therefore, any therapeutic attempts utilising IL-25 to treat cancer will need to be directed to tumour cells and must be used with caution given the potential to elicit pro-tumoural immune responses in the tumour microenvironment." (PMID 37455828, 2023). "However, IL-25 exerts a tumor regulatory role through different mechanisms, including eosinophil and B cell infiltration, apoptosis, and Th2 cytokines secretion in TME to create an immunosuppressive TIME." (PMID 37275901, 2023). "Although current studies indicate that IL-25 is primarily a tumor-promoting factor, IL-25 may hinder tumor progression under certain conditions." (PMID 37005677, 2023). "A previous study showed that genetic deletion of IL25 did not affect tumor burden caused by AOM and 2 cycles DSS treatment in BALB/c mice." (PMID 35359953, 2022). "Studies in APC-mutant mice found that decreased tumour burden upon IL-33-deficiency (but not IL-25-deficiency) is associated with reduced tumour mast cells, suggesting a potential pro-tumoral role downstream IL-33 signalling." (PMID 36263033, 2022). "On the other hand, genetic deficiency of IL-25 or rIL-25 treatment did not alter tumour Treg frequency in Apc1322T/+ mice, suggesting that tumour Tregs preferentially respond to IL-33 and not IL-25 in CRC." (PMID 36263033, 2022). "In addition, there was a slight and statistically insignificant correlation with stemness indices and tumor purity in both IL-25 and IL-17F." (PMID 36159856, 2022). "In the case of IL-25-dependent tumor progression, however, the use of IL-25 blocking methods, such as anti-IL-25 antibodies, may be complementary to the other anticancer agent." (PMID 35885460, 2022). "Finally, IL-25 injections inhibited heterotypic subcutaneous tumour growth across a range of human cancer cell lines in immunocompromised T cell-deficient nude mice, including a HT-29 CRC cell line." (PMID 36263033, 2022). "Angiogenesis blockers have proved beneficial clinically against CRC, and combined treatment through the inhibition of IL-25 or IL-33 may provide additional benefits to further reduce tumour angiogenesis." (PMID 36263033, 2022). "Colonic Vegfa expression was found to be reduced upon neutralisation of IL-25, or genetic IL-25-deficiency, in AOM/DSS-treated mice with CAC, suggesting that IL-25 may promote tumour VEGF-A expression." (PMID 36263033, 2022). "It has been shown that IL‐25 exerts conflicting functions in the tumor microenvironment." (PMID 34128588, 2021). "Therefore, non‐CSCs sustain CSCs in the tumor microenvironment through secretion of IL‐25 and contribute to cancer stemness." (PMID 34128588, 2021). "On the other hand, in the case of IL‐25‐dependent tumor progression, using IL‐25 blocking methods, including anti‐IL‐25 antibodies, might be a complementary approach to the other anticancer agent." (PMID 34128588, 2021).
tumor (continued). "In addition to blood components, IL‐25 and IL‐25R (IL‐17RB) expression have also been examined in different types of cancer cell lines and tumor tissues." (PMID 34128588, 2021). "The function of IL‐25 in cancers is primarily tumor‐supportive." (PMID 34128588, 2021). "Hence, we have tried to clarify the role of IL‐25 and its receptor in tumor progression and cancer prognosis." (PMID 34128588, 2021). "Furthermore, it has been indicated that administration of recombinant IL‐25 increases the viability, invasion, and migration of tumor cells, while blockade of IL‐25 with neutralizing antibodies leads to the apoptosis of tumor cells." (PMID 34128588, 2021). "In addition to the tumor‐supportive role of IL‐25, it has been clarified that this cytokine can also exert tumor‐suppressive function." (PMID 34128588, 2021). "The analysis of IL‐25 expression patterns in various tissues of cancer patients might imply the tumor presence in the body." (PMID 34128588, 2021). "Both of these processes may play an important role in tumor progression and drug resistance, and preclinical evidence indicates that blocking IL-25 signaling through its receptor (IL-17Rb) using a mAB may be an effective therapeutic route in PDAC." (PMID 32082375, 2019). "In addition, IL-25 immunostaining of HCC tumor tissue was significantly stronger than that of normal liver tissue of HH patients." (PMID 31296243, 2019). "Tumor microenvironments at both primary and metastatic sites are known to play an important role in metastasis, we thus examined the expression of IL-25 in both the primary tumor and the metastatic lung." (PMID 27909985, 2017). "Further studies suggest that these macrophages can be categorized into two groups: tumor-resident macrophages (CD206+YM-1+F4/80+Gr1-) and tumor-associated macrophages (CD206-YM-1- F4/80+Gr1-), with the former as the major tumor macrophage population that respond to anti-IL-25 antibody treatment." (PMID 27909985, 2017). "Of particular interests, recent studies suggest that IL-25 may play an anti-tumor role in several in vitro and in vivo systems." (PMID 27909985, 2017). "In addition, treatment with IL-25 was reported to reduce tumor growth in several xenograft tumor models, including melanoma, breast, lung, colon, and pancreatic cancers." (PMID 27909985, 2017). "While little is known about how IL-25 modulates tumor pathogenesis, recent studies have revealed it could prove to be an important therapeutic target." (PMID 27165713, 2016). "Contrary to our hypothesis, antibody suppression of IL-25 resulted in increased tumor burden compared to controls." (PMID 27165713, 2016). "The results revealed that the density of IL-25+IT cells (HR = 0.5; 95% CI, 0.3–0.9; p = 0.024), tumor location (HR = 0.5; 95% CI, 0.3–0.9; p = 0.016) and TNM stage (HR = 3.7; 95% CI, 1.9–7.1; p < 0.001) were independent prognostic factors for OS in patients with GC." (PMID 26840565, 2016). "Interestingly, even in vivo administration of anti-mouse IL-25 antibody was repeatedly found to detectably promote 4T1 metastasis, as compared with that of the control tumour-resected mice." (PMID 27089063, 2016). "In other words, Q2-3-induced IL-25 expression in the tumour microenvironment may positively regulate and promote the immunogenicity of tumour cells to host immunity." (PMID 27089063, 2016). "This suggested that IL-25 could mediate antitumor immunity by facilitating the recruitment of effector T cells to the tumor site." (PMID 26840565, 2016). "IL-25 expression may potentially be suppressed by active mechanisms in ATL since it exerts pro-apoptotic roles in other tumor types." (PMID 25340344, 2014). "Inhibiting IL25 signaling could hinder TC-mediated tumor promotion." (PMID 38892399, 2024).
tumor (continued). "On the other hand, there are some studies introducing IL-25 as one of the endogenous factors secreted by non-malignant mammary epithelial cells or tumor-associated fibroblasts conferring high cytotoxic activity on BC cells without affecting non-malignant mammary cells." (PMID 37835465, 2023). "A combination of IL-25 levels and tumor diameter may be an even more reliable predictor of OS." (PMID 36119529, 2022). "Gowhari Shabgah shows that utilizing IL-25-enhancing approaches, such as Virulizin® (mixture of proteins and peptides as immune response modifiers) and dihydrobenzofuran administration, has potentially inhibited tumor cell growth in cancers in which IL-25 has a tumor-suppressive function." (PMID 35885460, 2022). "In our results, it is confirmed that the expression of IL-17A, IL-17B, IL-17C, IL-17D, IL-17E (IL-25), and IL-17F in tumor immune subtypes is statistically significant, especially in BRCA; there may be a potential microenvironmental regulation mechanism that remains to be investigated." (PMID 36159856, 2022). "Therefore, they have suggested that using rIL‐25 might be useful to treat IL‐25‐expressing malignant tumor cells." (PMID 34128588, 2021). "In addition to prostate discrimination of inflammatory conditions from tumor microenvironment might be achieved through comparing the expression of IL‐25 in these two different microenvironments." (PMID 34128588, 2021). "Besides therapeutic approaches, IL‐25 dysregulation in body fluids, peripheral blood cells, and tumor tissue might be a valuable biomarker for predicting cancer prognosis." (PMID 34128588, 2021). "IL-25 promotes the progression of HCC through inducing alternative activation and CXCL10 secretion of macrophages in tumor microenvironment, and IL-25 secretion may partly result from hyperplastic epithelial tuft cells in colon, induced by gut microbiota dysbiosis." (PMID 31296243, 2019). "However, in another study, direct neutralization of IL-25 with a mAB in a chemically induced inflammatory model of CRC supports tumor progression, suggesting that the response to IL-25 therapy would likely be heavily dependent on the characteristics of the patient's TME." (PMID 32082375, 2019). "Because of the marked effect of the increased expression of IL-25 in Q2-3-mediated anti-metastasis, we would suggest that the IL-25/IL-25R interaction might also be considered as a new ‘immune check point' for activation of tumour immunogenicity." (PMID 27089063, 2016). "Therefore, mRNA levels of tumor-associated genes known to be important in the AOM/DSS model were assessed to establish whether IL-25 is capable of regulating genes involved in tumor development." (PMID 27165713, 2016). "IL-25 promotes ILC2s in tumors, maintaining tumor-infiltrating MDSC to form an immunosuppressive tumor microenvironment." (PMID 39309440, 2024). "In mice, IL-25-activated ILC2 cells were able to migrate to tumors, promote tumor growth and metastasis, and reduce the survival of mice." (PMID 37781372, 2023). "Transfer of IL25-activated ILC2 cells led to a significantly higher metastasis burden both in overall percentage of tumor area and number of tumor nodules." (PMID 37781372, 2023). "In this regard, they compared the levels of IL-25 in mouse (4T1) and human (MDA-MB-231) tumor cells treated with compound 37 using an immunoprecipitation method mediated by anti-IL-25 antibodies." (PMID 37765074, 2023). "While the resulting tuft cell - ILC2 feed-forward circuit promotes gastric metaplasia and tumor formation, genetic depletion of tuft cells or ILC2s, or therapeutic targeting of IL13 or IL25 alleviates these pathologies in mice." (PMID 37898600, 2023). "Taken together, these results indicate that IL25-activated ILC2 cells promote tumor growth, increase the metastatic potential of tumor cells, and reduce the survival of tumor-bearing mice." (PMID 37781372, 2023).
tumor (continued). "Overall, our results show that IL25-activated ILC2 cells preferentially migrate to tumors, and that they promote tumor growth and metastasis, as well as reduce survival of tumor-bearing mice." (PMID 37781372, 2023). "MSCs are able to deliver a variety of cytokines and growth factors to the tumor site that were identified as anti-tumor agents, comprising IFN-α, IFN-β, IFN-γ, IL-2, IL-7, IL-12, IL-15, IL-18, IL-25, and NK4, an antagonist of HGF." (PMID 37686315, 2023). "Specifically, individuals with high IL-25 levels exhibited higher AFP levels, greater viral loads (≥2,000 IU/ml), and larger tumor sizes (all p < 0.05), indicating that higher IL-25 levels are associated with more advanced HCC." (PMID 36119529, 2022). "Collectively, these studies suggest that IL-25-mediated activation of ILC2s, and IL-33-mediated stimulation of Th2 cells, may act as independent parallel pathways to induce the production of IL-4 and IL-13 leading to the activation of MDSCs to suppress anti-tumour T cells and promote CRC." (PMID 36263033, 2022). "The nomogram C-index value (0.726) for OS was higher than that for IL-25 (0.559), HBV-DNA (0.569), AFP (0.584), encapsulation of tumor (0.591), and diameter of tumor (0.635) (all p < 0.05)." (PMID 36119529, 2022). "In the past decade, emerging studies have begun to uncover the previously unappreciated role of IL-25 and IL-33 in CRC disease pathogenesis and in shaping the tumour niche, with distinct effects specific to the different subtypes of CRC." (PMID 36263033, 2022). "IL25 treated CRC cells substantially enhanced the expression levels of CD133 and LGR5, the formation of tumor organoid and sphere, thus decreasing the sensitivity to oxaliplatin of CRC cells." (PMID 35359953, 2022). "Emerging studies in the past decade have found IL-33 and IL-25 to either promote or inhibit CRC under different settings, and is likely dependent on the CRC subtype, tumour immunogenicity and the different immune cell populations involved." (PMID 36263033, 2022). "The conditioned media immunodepleted for IL-25 from cultivation of mouse and human fibroblasts were also employed to culture 4T1 and MDA-MB-231 tumour cells, respectively." (PMID 27089063, 2016). "The concentrations of the following cytokines including IL-23, IL-25, IFNγ, CD40L and TNFα in WF collected from patients with T2 tumor tended to be higher than those with T1 tumor." (PMID 26313265, 2015). "Specifically, IL‐25 stimulation enhanced ILC2‐driven recruitment of MDSCs, which inhibit CD8+ T cell activity and accelerate tumour growth; blocking this IL‐25/ILC2 axis reverses immunosuppression and reduces tumour burden, highlighting its therapeutic potential." (PMID 40899118, 2025). "Here, we found that IL25 expression is negatively correlated with survival of human NSCLC patients, that ILC2 cells are elevated in human NSCLC patients and that IL25-activated murine ILC2 cells promote lung tumor growth and metastasis while reducing survival of tumor-bearing mice." (PMID 37781372, 2023). "In conclusion, IL-25 can bind to the receptor and activate multiple downstream signaling pathways, including NF-κB, MAPK, JAK and STAT3, which play diverse roles in self-renewal, survival and apoptosis of cells as well as inflammation, tumor progression." (PMID 37005677, 2023). "IL-25, an IL-17 cytokine subfamily member in TME or TIME, transforms inflammatory ILC2s (iILC2s) to natural ILC2s (nILC2s) or ILC3-like cells to create an innate tumor-permissive microenvironment through activating ILC2s via inducing IL-17 expression." (PMID 37275901, 2023). "Briefly, IL-25 is produced by rare tuft cells in the intestines and may promote CRC tumorigenesis through directly inducing tumour stemness or indirectly via stimulation of ILC2s which activates MDSCs." (PMID 37455828, 2023). "Taken together, these findings suggest that the IL25/ILC2 axis and Tregs may concomitantly contribute to a tumor-promoting environment in human NSCLC." (PMID 37781372, 2023).